Y_RNA (Y RNA )
Gene: Miscellaneous RNA gene on chromosome 1 (27,255,464 to 27,255,567, reverse strand). Ensembl gene ENSG00000252098.
Homologues: Orthologues: chimpanzee Y_RNA (100% identical). Paralogues in human: RNY1 (87% identical), Y_RNA (87% identical), Y_RNA (86% identical), Y_RNA (85% identical), RNY1P11 (84% identical), Y_RNA (84% identical), Y_RNA (83% identical), Y_RNA (82% identical), Y_RNA (81% identical), RNY1P12 (80% identical), RNY1P8 (80% identical), Y_RNA (80% identical), and 97 more.